ZNF233 (zinc finger protein 233)
Description:
May be involved in transcriptional regulation.
Synonyms: FLJ38032
Tractability: PROTAC: ubiquitination databases record sites on it.
Gene: Protein-coding gene on chromosome 19 (44,259,880 to 44,275,878, forward strand). Ensembl gene ENSG00000159915.
Subcellular location: Nucleus
Subcellular location (Human Protein Atlas): Nucleoplasm
Pathways (Reactome):
Gene expression (Transcription): Generic Transcription Pathway
Gene Ontology:
Molecular function: DNA-binding transcription factor activity
Biological process: regulation of DNA-templated transcription
Cellular component: nucleus
Genetic constraint (gnomAD): Loss-of-function variants: 6 observed, 9.84 expected, observed/expected ratio (o/e) 0.61, 90% interval 0.33 to 1.2. That is too few expected variants to judge how well the gene tolerates losing a copy. Missense variants: 696 observed, 812.38 expected, observed/expected ratio (o/e) 0.86, 90% interval 0.8 to 0.91. Synonymous variants: 224 observed, 282.08 expected, observed/expected ratio (o/e) 0.79, 90% interval 0.71 to 0.89.
Homologues: Orthologues: chimpanzee ZNF233 (97% identical), macaque ZNF233 (92% identical), mouse Zfp235 (46% identical), rat Zfp108 (46% identical), rat Znf235 (45% identical), mouse Zfp93 (45% identical), mouse Zfp108 (44% identical), mouse Zfp109 (42% identical), mouse Zfp114 (40% identical). Paralogues in human: ZNF285 (39% identical), ZNF155 (33% identical), ZNF230 (33% identical), ZNF214 (33% identical), ZNF223 (32% identical), ZNF222 (31% identical), ZNF287 (31% identical), ZKSCAN7 (28% identical), ZNF852 (28% identical), ZNF34 (28% identical), ZNF17 (27% identical), ZNF527 (27% identical), and 38 more.
Diseases named in the same sentence as ZNF233 in open-access papers:
ZNF233 is named in the same sentence as 2 diseases in open-access papers, as found by Europe PMC text mining. Sharing a sentence is not in itself a finding about the gene and the disease. The quoted sentences say what the papers report.
tumor (1 paper, 2023). "Interestingly, some of the common down-regulated genes, such as EPHA7 and NSUN7, are known for both their tumor suppressing and promoting roles, or are associated with overall survival (OS) (SLC22A31), while others have clear pro-tumorigenic roles (ADGRF1, LOX, LY6G5C, SNAI2, TNFRSF11B, ZNF233)." (PMID 36769365, 2023).
ZNF233 also shares sentences with these, for which no sentence is quoted: breast carcinoma (1 paper).